IL6 (interleukin 6)
Diseases named in the same sentence as IL6 in open-access papers (continued):
Sharing a sentence is not in itself a finding about the gene and the disease.
tumor (continued). "These immune cells can produce cytokines such as IL-6, IL-10, TNF-α, and MCP-1, and are interconnected with tumor cells in an autocrine and paracrine manner." (PMID 32974180, 2020). "Using HCC cell-line analysis, we showed that STC1 exerted inhibitory action on the growth of tumor spheroids in culture, reduced the pro-migratory effects of IL-6/IL-8 on HCC, and diminished the development of tumor mass in nude mice model." (PMID 33156861, 2020). "IL-6, a major mediator of inflammation, induces the expression of STAT3 target genes and drives tumor growth and/or survival." (PMID 32883032, 2020). "Tumor cell-derived EVs stimulate MMP-9, IL-6, and transforming growth factor-β (TGF-β) and induce the secretion of EMMPRIN, which, in the tumor microenvironment, drives immune evasion, invasion, and inflammation that promote tumorigenesis." (PMID 32948029, 2020). "We therefore examined secretome profiles of tumour-conditioned (BLM-CM and OMC-CM) and control media (Fb-CM and OSC-CM), and focused our attention on CCL-2, IL-6 and PGE2, factors known to play a role in tumour modulation of myeloid functions." (PMID 32488012, 2020). "IL-6, periostin, LIF, and prostaglandin E2 (PGE2), are CAF-derived soluble factors that have been described to play a role in tumour progression." (PMID 33060625, 2020). "Specifically, cryo-thermal therapy-induced IL-6-rich acute pro-inflammatory response promotes DC phenotypic maturation, CD4(+) T cell differentiation, and Th1 anti-tumor immunity." (PMID 33240283, 2020). "MDSCs promote tumor epithelial–mesenchymal transformation (EMT) by expressing factors, such as TGFβ, IL-6, hepatocyte growth factor (HGF), and high mobility group binding (HMGB)-1, which makes tumors exhibit aggressive phenotypes with high migration ability." (PMID 32942545, 2020). "IL-1 induces EMT transition, transdifferentiation, and metastasis and supports tumor growth and metastasis by inducing autocrine and paracrine secretion of molecules such as VEGF, IL-6, and IL-8." (PMID 33326447, 2020). "It was reported that autophagy was able to secrete some specific factors, such as interleukin-6, MMP-2, and WNT-5A, which was required for tumor cell invasion." (PMID 33004792, 2020). "We focused on IL-6, which has been reported to be produced by HSCs in the HCC microenvironment, where it facilitates tumor progression." (PMID 32632241, 2020). "The increased production of these inflammatory proteins is responsible for several types of cancer and the overexpression of these proteins (especially IL-6 and MMP-9) predict for a worse prognosis and an aggressive tumor phenotype." (PMID 32211076, 2020). "This is in accordance with the observed reduction of the pro-tumorigenic factors IL-6, periostin, LIF and, PGE2 which previously have been shown to promote tumour cell growth." (PMID 33060625, 2020). "In particular, IL-6 is a key mediator in inflammation and carcinogenesis, such as EMT, metastasis and tumor microenvironment." (PMID 32856877, 2020). "The increased expression of numerous proinflammatory cytokines, including IL6 and TNFα and chemokines involved in immune cell chemotaxis observed via bulk RNA sequencing, could support trafficking and maturation of various immune cell populations to and from the tumor tissue." (PMID 32754281, 2020). "For example, chemokines (e.g., TNF-α, IL-6, and IL-1b) recruit immunosuppressive neutrophils and M2 macrophages to the TME, thereby inhibiting anti-tumor cell activity (e.g., TCD 8+ lymphocytes and NKTs)." (PMID 32208363, 2020). "In sarcoma and prostatic adenocarcinoma, CAFs secrete TGF-β, IL-6 and tumor necrosis factor-alpha (TNF-α) that activate YAP1/TAZ and NFκB signaling in tumor cells, resulting in inhibition of tumor cell proliferation." (PMID 33114328, 2020). "In tumor cells, hyperactivated STAT3 promotes the expression of immunosuppressive factors such as VEGF, IL-6, and IL-10." (PMID 32972405, 2020).
tumor (continued). "To determine the effects of chronic restraint stress and XYS on liver metastasis, we examined the expressions of TGF-β, IL-6, MMP-9 and VEGF in spleen tumours by RT-PCR and Western blot analysis." (PMID 33152259, 2020). "In many human cancers, an abnormally hyperactivated IL-6/STAT3 signaling has been observed in tumor cells and cells of the tumor microenvironment, and pro-tumorigenic characteristics of both, IL-6 and STAT3, have been described." (PMID 33257655, 2020). "We showed that atorvastatin treatment decreased the levels of IL-6, p-STAT3, and TERT but increased β-gal expression and SA-β-gal activity in tumor lesions." (PMID 32257389, 2020). "We investigated the interplay between activin A and IL‐6 in the cachexia‐inducing TOV21G cell line, both in culture and in tumours in mice." (PMID 31436048, 2020). "High plasma levels of IL-6, TNF-α, INF-γ, and IL-1β have been observed in both tumor-bearing animals and cachectic cancer patients." (PMID 31941005, 2020). "The increased levels of adipose tissue-derived factors, such as TNF-α, IL-6, IL-8, macrophage chemoattractant protein (MCP-1), and leptin, and their role in tumor progression have been well-documented." (PMID 32847136, 2020). "Co-culture of BMDM with tumour cells led to increased expression of iNOS and CD206, and Il1α, Il1β, Il6 and Tgfβ in the BMDM." (PMID 32792542, 2020). "C-PC/CMC-CD55sp nanospheres played an important role in tumor suppression, reduced the expression TGF-β, and increased IL-6 and TNF-α." (PMID 32636744, 2020). "On one hand, neutrophils secrete tumor growth factors, cytokines, and chemokines, including TGF-beta, VEGF, IL-6, IL-8, IL-12, and matrix metalloproteinase, which can promote angiogenesis." (PMID 32656072, 2020). "In cells of a granulosa-like tumor cell line (KGN), overexpression of GAS5 led to upregulated IL-6, while silencing of GAS5 played an opposite role." (PMID 33308258, 2020). "In fact, IL-6 and HGF increased the stemness of CSC subpopulations from primary and established tumor cell lines and induced in vivo tumorigenic capacity." (PMID 32660072, 2020). "IL-6 activates STAT3 phosphorylation, inducing the transcription of genes that regulate tumor cell proliferation and antiapoptosis." (PMID 32742470, 2020). "In fact, the activation of NF-kB leads to the release of IL-6, IL-12, IL-17 and IL-18 as well as the tumor necrosis factor alpha (TNF-alpha), triggering persistent inflammation in the tumor microenvironment." (PMID 32878124, 2020). "This indicated that FLP ointment significantly decreased the expression of IL-6, IL-1β, and TNF-α in exosomes, serum, lung, and tumour tissues." (PMID 32308722, 2020). "MSCs are agitated to migrate towards tumor tissues via various factors excreted by tumor cells, including SDF-1, IL-6 or PDFG." (PMID 32268527, 2020). "Impressively, complete tumour regressions were seen in 80–100% of the treated mice, the drug was well-tolerated, and a significant increase in IFN-β, IL-6 and tumour necrosis factor-α were observed in tumour and plasma." (PMID 33081170, 2020). "Macrophages and adipocytes produce pro-inflammatory factors, resulting in elevated concentrations of circulating tumour necrosis factor-α (TNF-α), interleukin-6 (IL-6) and C-reactive protein (CRP), which are beneficial for tumour growth." (PMID 32210471, 2020). "In a CAC model, oral pre-treatment with S. gallolyticus exacerbates both inflammation (e.g., IL-6, IL-1β, IL-8, CCL2, TNFα) and tumor formation." (PMID 32962159, 2020). "F. nucleatum infection enhanced the tumor growth of CRC in a TLR4-dependent manner, and the effect involved activation of the IL-6/p-STAT3/c-MYC signaling pathway." (PMID 33488528, 2020). "Moreover, CAF-derived IL-6 promotes BC cell growth and invasion through induction of Notch-3, Jagged-1, and carbonic anhydrase IX, all of which may represent attractive targets for developing new anti-tumor therapies." (PMID 32604738, 2020).
tumor (continued). "We performed ELISA assay to determine the expression of IL6 and TNF-α in the blood of tumor-bearing mice." (PMID 32742480, 2020). "For example, out of the SASPs, IL-6, IL-8, and CCL2 enhance tumor cell proliferation; VEGF promotes angiogenesis; IL-6, IL-8, IGFBP7, and PAI-1 augment senescence." (PMID 32215170, 2020). "Adipocytes in the omentum secret cytokines and chemokines, such as IL-6, IL-8, MCP-1, tissue inhibitor of metalloproteinases-1, and adiponectin, to promote transcoelomic metastasis and tumor progression." (PMID 33123161, 2020). "We found that these receptors are highly correlated to the innate and adaptive immunity-related cells, as well as IL-10, IL-6, CXCL10, CCL2-CCL5, TGFB1 in KIRC tumors, whereas in KIPRP tumor tissues IL8, IL1A, and TNF were highly correlated." (PMID 33330620, 2020). "Most importantly, IL-6 leads to the activation of STAT3 and overexpression of downstream tumor-suppressor genes in HNSCC, which subsequently propels the reinforcement of tumor cell expansion and migration." (PMID 33203092, 2020). "In addition, it was also reported that basophils could release pro-inflammatory cytokines such as TNF-α, IL-6 and IL-1β, which augmented the inflammatory anti-tumor reaction, resulting in direct anti-neoplastic functions and inducing the apoptosis of tumor cells." (PMID 32037496, 2020). "TAM-derived IL-10 and interactions with MDSCs result in decreased IL-6, IL-12, and MHCII, and increased anti-inflammatory IL-10, TGF-β1, and Foxp3+ Treg frequencies to facilitate tumor growth and immune tolerance." (PMID 33718121, 2020). "Such cytokines IL-8, IL-6, IL-1β, TNF-α, IL-10, and others can be up-regulated and consequently contribute to tumor progression." (PMID 32277014, 2020). "As we previously reported that activated HSCs promote cancer cell progression through paracrine or autocrine IL-6, it is known that secretion of CAFs and activated HSC regulate downstream pathways and promote tumor growth." (PMID 33346211, 2020). "HuR has high binding affinities for the 3′-UTRs of angiogenic factors (VEGF, COX-2, IL-8), an immunomodulating factor (IL-6), TGF-β, and TNF-α, and thus plays important roles in regulating tumor proliferation and angiogenesis in the central nervous system." (PMID 32967226, 2020). "In particular, the endothelial cells present in the tumor have an accelerated cell cycle, greater migratory abilities and also secrete factors like IL-6, IL-8, MCP-1, and GRO-a that can promote tumor progression and metastasis." (PMID 32292409, 2020). "Although there was a slight difference in the IL-6 and TNF-α mRNA levels, the IL-1β cytokine levels were elevated in tumours injected with IL-33." (PMID 33308251, 2020). "We utilized an explant culture model and cultured cells isolated from CRC tumor tissues to examine the effect of HDAC inhibition and IL-6 neutralization on the expression of genes related to MDSCs function or recruitment." (PMID 31941522, 2020). "It is well established that IL-6 and its overexpression has a detrimental role in early CRC tumorigenesis by promoting tumor growth and invasion." (PMID 33327620, 2020). "Our present study revealed that TU-100 inhibited tumor growth of cancer cells by suppressing HSC activation and decreasing IL-6 secretion from HSC, as well as inducing directly the autophagy of cancer cells." (PMID 33346211, 2020). "Associations among fecal occult blood test (FOBT) result, CD68, IL-6, and TNF-α expression in tumor cells." (PMID 33643891, 2020). "Tumor-infiltrating T, B, and NK cell levels and plasma concentrations of Th1 (IL-2, IFN-γ, and TNF-α), Th2 (IL-4, IL-5, IL-6, and IL-10), Th9 (IL-9), and Th17 (IL-17A, IL-17F, IL-21, and IL-22) cytokines were evaluated." (PMID 32802733, 2020). "We compared normal and tumor tissues for MK2 downstream cytokine production and also found a significant increase in IL-1β, IL-6, and TNF-α in tumors with lymph node metastasis compared to non-metastatic tumors." (PMID 32216812, 2020).
tumor (continued). "In parallel, inflammatory cytokines sustained the levels of CSCs, and recombinant IL-6 and CXCL8 increased the formation of tumor spheres by CD90+ tumor cells." (PMID 33585241, 2020). "In supernatants from tumour cell killing assays, we found a similar immune mediator profile (TNFα, MCP-1, IL-10, CXCL-10, IL-1β, IL-6, and IL-23) to that previously detected with IgE cross-linking on the surface of monocytes." (PMID 33203088, 2020). "One study established a positive feedback signaling loop formed by TGF-β and IL-6/JAK2/STAT3 signaling pathways, which mediates interactions between MF and tumor cells." (PMID 33262947, 2020). "They promote angiogenesis via VEGF, promote tumor development and metastasis through cathepsin G and ROS, induce chronic inflammation by releasing TNF-α, IL-1β, IL-6, and IL-12, and inhibit effector CD8+ T cells." (PMID 32499786, 2020). "CSCs recruit macrophages to the tumor niche by producing pro-inflammatory cytokines and chemokines, such as CCL2, IL-6, IL-4, VEGF and TGF-ß." (PMID 33059744, 2020). "Classical activation of M1 macrophages in response to IFN-γ is characterized by a high ability to express antigens, high expressions of iNOS, IL-6, TNF-α, IL-1β mRNA, and nitric oxide (NO), which can kill endogenous pathogens and tumor cells." (PMID 33240950, 2020). "Cytokines, such as tumor necrosis factor alpha (TNF-α), interleukin-6 (IL-6), and transforming growth factor-beta (TGF-β), are the major mediators which are responsible for interchanging among cells in the tumor microenvironment." (PMID 32123532, 2020). "Cytokine IL-6, a major mediator of inflammation and activator of STAT3, serves to block apoptosis and promote tumor survival." (PMID 32576206, 2020). "Studies have shown that the mechanism of microvessel proliferation and basal membrane degradation in other diseases, such as cancers and strokes, involves the JAK2/STAT3, IL-6/JAK2/STAT3, and MMP-9 pathways, which regulate the progression of tumor metastasis." (PMID 32047820, 2020). "Tumor cytokines’ dynamics indicate that as the tumor grows, HMGB1, IFN-γ and μ1 (IL-6, IL-17, IL-21, IL-22) increase in density, but TGF-β and μ2 (IL-10, CCL20) stay relatively constant." (PMID 33291412, 2020). "Cytotoxicity against CD155 positive tumor cells was enhanced with an increased level of cytokines, such as IFN-γ, IL-6, and TNF-α." (PMID 32882824, 2020). "Increased IL-6 and FFA levels were noted in mice with developing neoplasm, both in the early and late stages." (PMID 33327591, 2020). "Blocking CD47 also increases the reactivity of anti-tumor T and NK cells and increases the release of various cytokines, including IFN-γ and IL-6." (PMID 32000802, 2020). "To investigate the influence of exogenous IL-33 on pro-inflammatory factors, such as IL-6, IL-1β, and tumour necrosis factor (TNF)-α, we measured their mRNA expressions, which are known to stimulate tumour proliferation and angiogenesis." (PMID 33308251, 2020). "IL-6 then triggers the signal transducer and activator of transcription 3 (STAT3) pathway in immune cells, stromal cells, and tumour cells." (PMID 33081785, 2020). "The ELISA results indicated that PZH indeed decreased the levels of IL-6 and TNF-α in tumor tissue homogenates from HCC mice." (PMID 33344655, 2020). "Of note, it has been shown that long noncoding RNA TSLNC8 blocks tumor growth by reducing the interaction between TKT and STAT3 and inhibiting IL-6/STAT3 signaling pathway." (PMID 31949131, 2020). "BMAs secrete a large amount of IL-6, which induces EMT in cancer cells through the JAK2/STAT3 pathway and increases the metastatic potential of tumor cells by promoting tumor cell survival through the PI3K/AKT pathway." (PMID 32674405, 2020). "MiR-155 is also related inflammation since IL-6 induces its expression and this in turn activates the JAK2/STAT3 pathway, thus promoting tumor inflammation." (PMID 33059744, 2020).
tumor (continued). "Macrophages of mice with intestinal dysbacteriosis release pro-tumorigenic cytokines (e.g., IL-6 and TNF) and stimulate in vivo the growth of tumor xenografts, while promoting colon cancer cell proliferation and EMT in vitro." (PMID 32962159, 2020). "Through all these pre-clinical studies, we can conclude that IL-6 is a potent inflammatory cytokines and activator of STAT3, produced not only by tumor cells but also by cells in the PMN." (PMID 33322216, 2020). "Several other pro-inflammatory targets leading to potentially tumor-toxic effects, such as CCL17, IFNγ, IL1β, and IL6, were increased in tendency." (PMID 32316245, 2020). "Pro-inflammatory cytokines, such as IL-6 and LIF, are aberrantly expressed by CAFs in the tumor microenvironment and induce chemoresistance as well as EMT." (PMID 32546182, 2020). "Pro-inflammatory cytokines such as IL-1β, IL-6 and TNF-α, secreted by microglia, have been shown to increase tumor invasiveness in vitro." (PMID 32765498, 2020). "TLR4, iNOS, IL-6, MIP-3α and VEGF were highly expressed in the transplanted tumor tissues from the LPS groups, and their expression levels were decreased in the TLR4-silenced groups." (PMID 32095158, 2020). "Cisplatin treatment increased both IL-6 and IL-8 message levels in all sample types, especially in the EGFR mutant tumor samples." (PMID 32434541, 2020). "As expected, treatment with rosiglitazone was able to decrease IL6 and IL1Ra production by macrophages exposed to BCC-CM of both tumor cell lines." (PMID 31936729, 2020). "It is therefore expected that tumor cells would be able to use TNF-α and IL-6 signaling to their own advantage." (PMID 33178579, 2020). "Other adipocyte-secreted factors have been described to promote tumor cell resistance to TKI, including the tissue inhibitor metalloproteinase-1 (TIMP-1), interleukin-6 (IL-6), the fibroblast growth factor (FGF) and neuregulin-1 (NRG-1)." (PMID 32795383, 2020). "By IHC analysis, we demonstrated that the expression levels of CD68, IL-6 and TNF-α in tumor cells of FOBT-positive patients were significantly higher than those in FOBT-negative patients." (PMID 33643891, 2020). "As we previously reported that activated HSCs promote cancer cell progression through paracrine or autocrine IL-6, it is known that activated HSC regulate downstream pathways and promote tumor growth." (PMID 32895059, 2020). "In the tumor microenvironment, IL6/JAK/STAT3 signaling drives proliferation, survival, invasiveness, and metastasis of tumor cells, while strongly suppressing the anti-tumor immune response." (PMID 32957689, 2020). "Importantly, it has been demonstrated that Il-6, Il-11, Osm, Lif, and Cntf are expressed by osteoblast-lineage cells and that Ct-1 is expressed by osteoclasts, suggesting that tumor cells in the bone marrow will encounter these signals in the physiological bone marrow microenvironment." (PMID 32023849, 2020). "TAMs secrete inflammatory cytokines and factors such as interleukin 6 (IL-6), interleukin 10 (IL-10), and TGF-β in the tumor microenvironment, which facilitate the inflammatory microenvironment to promote cancer progression and metastasis." (PMID 32326073, 2020). "The expression of IL-8, IL-6, and MIP-3α in the macrophages was determined by RT-qPCR, that of IL-8, IL-6, and MIP-3α in the tumor microenvironment detected by immunofluorescence and their levels in the culture medium of co-cultured cells measured using ELISA." (PMID 33363140, 2020). "Like IL-6, IL-8 is highly expressed and secreted from GBM cell lines, tumor stem cells and human specimens." (PMID 32973662, 2020). "A variety of cytokines released by MCs including IL-1, IL-4, IL-8, IL-6, MCP-3, MCP-4, TNF-α, IFN-γ, LTB4, TGF-β, and chymase contribute to developing inflammation, inhibiting tumor cell growth, and inducing tumor cell apoptosis." (PMID 31256327, 2020).